YY1 (YY1 transcription factor)
Diseases named in the same sentence as YY1 in open-access papers (continued):
Sharing a sentence is not in itself a finding about the gene and the disease.
head and neck squamous cell carcinoma (5 papers, 2020 to 2023). A squamous cell carcinoma that arises from any of the following anatomic sites: lip and oral cavity, nasal cavity, paranasal sinuses, pharynx, larynx, and salivary glands. "In head and neck squamous cell carcinoma, YY1 expression goes toward an up-regulation while YY1 depletion strengthens cell apoptosis and interferes cell proliferation, migration and invasion." (PMID 35778739, 2022). "The aim of this study was to explore the expression of YY1 and CP2 in head and neck squamous cell carcinoma (HNSCC) patients and their association with survival." (PMID 33315124, 2021).
Hyperglycemia (5 papers, 2017 to 2025). An increased concentration of glucose in the blood. "During T2D progression, chronic hyperglycemia and lipotoxicity exacerbate YY1-mediated transcriptional control of anabolic pathways." (PMID 41459495, 2025). "Collectively, YY1 mediated hyperglycemia-induced Pim3 expression, both in HG-treated H9C2 cells and in streptozotocin-induced diabetic hearts." (PMID 39850120, 2025). "Pretreatment of CFs with colivelin TFA markedly enhanced hyperglycemia-induced YY1 nuclear translocation, cell proliferation and activation, and ECM protein up-regulation, while DAPA did not reverse these effects." (PMID 41170186, 2025). "In contrast, hyperglycemia-driven YY1 upregulation in diabetic tissues represses oxidative and mitochondrial genes; normalization of glucose levels reverses this effect." (PMID 41459495, 2025). "Specifically, hyperglycemia upregulated YY1 expression in smOGTWT aortic vessels (2.9-fold vs. normoglycemic smOGTWT; p < 0.0005)." (PMID 37175604, 2023). "Indeed, YY1 participated in hyperglycemia-induced CF proliferation and activation, ECM protein up-regulation, and subsequent myocardial fibrosis." (PMID 41170186, 2025). "Taken together the findings point to a vicious cycle in which elevated nutrients, partly via Yy1, decrease Sox5 expression and lead to impaired insulin secretion, which in turn may aggravate the hyperglycemia." (PMID 28585545, 2017). "Yin Yang 1 (YY1), which translocated from the cytoplasm into the nucleus under hyperglycemia, bound to the Pim3 promoter and enhanced Pim3 transcriptional activity." (PMID 39850120, 2025). "The protein expression of ANP and β-MHC was significantly higher in HG-treated H9C2 cells than in the control group (P<0.05), while treatment with YY1 siRNA, but not scrambled siRNA, mitigated this hyperglycemia-induced effect (P<0.05)." (PMID 39850120, 2025). "As such, we speculate that interaction of YY1- and SRF-dependent pathways drive OGT-mediated SMC transformation to a de-differentiated phenotype in response to hyperglycemia." (PMID 37175604, 2023). "Furthermore, the mRNA and protein expression of Pim3 was significantly up-regulated when H9C2 cells were exposed to HG compared with the control group (P<0.05), while treatment with YY1 siRNA, but not scrambled siRNA, markedly attenuated these hyperglycemia-induced effects (P<0.05)." (PMID 39850120, 2025).
idiopathic pulmonary fibrosis (5 papers, 2019 to 2026). Idiopathic pulmonary fibrosis (IPF) is a nonneoplastic pulmonary disease that is characterized by the formation of scar tissue within the lungs in the absence of any known cause. "YY1, RTN4, RICTOR, SFPQ, LARP6, and HELLS have been associated with cancers previously and, in this study, exhibited differential level changes between control, Idiopathic Pulmonary Fibrosis (IPF) and lung cancer cells." (PMID 37569873, 2023).
Intellectual disability (5 papers, 2018 to 2025). "GADEVS, a rare congenital condition characterized by intellectual disability (ID) and multiple physical/behavioral abnormalities, has recently been linked to YY1 gene caused by either heterozygous sequence variants or deletions involving the entire gene." (PMID 39775551, 2025). "YY1 plays a critical role in cortical development and haploinsufficiency of YY1 causes “YY1 syndrome”, a neurodevelopmental disorder characterized by intellectual disability, seizures, and behavioral impairment." (PMID 35013139, 2022). "Strikingly, the missense variants in the YY1 gene that cause intellectual disability, also appear to cluster in the zinc finger domains, with different variants affecting the identical amino acid residue." (PMID 29573576, 2018).
brain tumor (4 papers, 2010 to 2024). "For this purpose, we queried the Oncomine database and found that 4 PcG genes (EZH2, RBBP7, SUZ12, YY1) are specifically expressed in brain tumors." (PMID 20920292, 2010).
breast tumors (4 papers, 2008 to 2025). "Surprisingly, we also observed a strong association between AP-2α and YY1 expression levels in the primary breast tumors (p < 0.001)." (PMID 18218085, 2008). "The goals of this study were to characterize better the relationship between the overexpressions of ERBB2 and AP-2α in primary breast tumors and to analyze the implication of the YY1 protein as a cofactor of AP-2." (PMID 18218085, 2008). "ERBB2, AP-2α, and YY1 protein levels were analyzed by immunohistochemistry in a panel of 55 primary breast tumors." (PMID 18218085, 2008). "This study highlights the role of both AP-2α and YY1 transcription factors in ERBB2 oncogene overexpression in breast tumors." (PMID 18218085, 2008). "Our results further suggest that ERBB2 overexpression in breast tumors results not only from a high expression of AP-2α but also from the concomitant high expression of YY1." (PMID 18218085, 2008). "It was hypothesized that patients with breast tumors demonstrating YY1 overexpression would show improved prognosis via suppression of the oncogenic function of CP2c." (PMID 37444605, 2023). "Moreover, in the present study, we observed a strong correlation between AP-2α and YY1 protein levels in the primary breast tumors and a decrease in the AP-2α and AP-2γ levels following transfection of an siRNA targeting YY1." (PMID 18218085, 2008). "For clinical validation, while we confirmed elevated expression of SPANXB1 and its downstream effectors (YY1, H3R17me2, MMP1) in both primary breast tumors and brain metastases, the small sample size (n = 5 per group) necessitates validation in larger clinical cohorts." (PMID 40885703, 2025).
Cerebral ischemia (4 papers, 2013 to 2023). Restriction of arterial blood supply to the brain associated with insufficient oxygenation to support the metabolic requirements of the tissue. "In the cerebral ischemia/reperfusion (CI/R) model, YY1 binds to lncRNA GAS5 to form a complex that fosters PFKFB3 transcription, glycolysis, and neuronal apoptosis." (PMID 37184686, 2023). "Consistently, in a previous study, YY1 knockdown was shown to decrease ischemic brain damage and improve overall neurological functions in mice with cerebral ischemia/reperfusion injury, and YY1 overexpression was found to be involved in OGD-induced neuron apoptosis." (PMID 33722608, 2021). "Besides, it has been established in an earlier study that YY1 can induce neuronal glycolysis to trigger cerebral ischemia/reperfusion injury in vivo." (PMID 33722608, 2021). "While the data presented here identified both YY1 and RelA as repressors of the Bim gene, role of RelA as a Bim repressor came in as a surprise because a previous report on RelA in cerebral ischemia model suggested that RelA is a transcriptional activator of the Bim gene." (PMID 23874387, 2013). "Meanwhile, YY1 adversely modulates GAS5 expression by binding to the GAS5 promoter and thus represses its transcription in neurons following cerebral ischemia/reperfusion injury." (PMID 34497757, 2021).
Cognitive impairment (4 papers, 2022 to 2026). Abnormal cognition is characterized by deficits in thinking, reasoning, or remembering. "YY1 deletions and point mutations lead to syndromic ID with a wide variety of phenotypic features, including cognitive impairment, behavioral alterations, intrauterine growth restriction because of transcriptional and chromatin dysfunction." (PMID 35436926, 2022). "A recent study suggests that YY1 can be used to modulate stem cells as a potential treatment for severe mental disorders and cognitive impairments." (PMID 38739758, 2024). "How YY1 and GRM1 haploinsufficiency leads to inherited cognitive impairment and spinocerebellar ataxia visible from birth is currently unknown." (PMID 41902692, 2026).
Duchenne muscular dystrophy (4 papers, 2017 to 2025). Duchenne muscular dystrophy (DMD) is a neuromuscular disease characterized by rapidly progressive muscle weakness and wasting due to degeneration of skeletal, smooth and cardiac muscle. "Moreover, miR-21 has been shown to contribute to muscle atrophy following denervation through regulating YY1 protein and play an important role in muscle fibrosis during Duchenne muscular dystrophy." (PMID 32340146, 2020).
Dystonia (4 papers, 2024 to 2026). An abnormally increased muscular tone that causes fixed abnormal postures. "Only recently, the zinc finger transcription factor encoded by YY1 (yin and yang 1), involved in oligodendrocyte maturation and initiation of myelin formation, was linked to a neurodevelopmental disease with variable dystonia." (PMID 41518464, 2026). "The YY1 gene encodes the zinc-finger TF protein yin and yang 1 that interacts with the dystonia-associated gene THAP1 and activates the myelination gene expression program centered on the TF EGR2, thus highlighting the crucial role of YY1 in central nervous system myelination." (PMID 38042508, 2024). "Notably, YY1 has been implicated in genetic forms of dystonia." (PMID 38042508, 2024).
endometrial cancer (4 papers, 2015 to 2021). Primary or metastatic malignant neoplasm involving the endometrium (mucous membrane that lines the endometrial cavity). "Both the PI3K/AKT and Wnt/b-catenin signaling pathways modulate the CSC phenotype in endometrial cancer; thus, YY1 might regulate the CSC phenotype, leading to worse clinical outcomes." (PMID 33728560, 2021). "Additionally, YY1 was shown to silence APC gene expression in endometrial cancer cells by enhancing EZH2-mediated H3K27me3 deposition on the APC promoter." (PMID 33728560, 2021). "YY1 is required to promote the recruitment of EZH2 to the miRNA-361 promoter, suggesting that YY1 governs the CSC phenotype in endometrial cancer." (PMID 33728560, 2021).
head and neck cancer (4 papers, 2020 to 2025). A primary or metastatic malignant neoplasm affecting the head and neck. "In head and neck cancer, the mutation of laminin alpha 5 (LAMA5) gene can increase the expression of YY1." (PMID 35791393, 2022).
myocardial infarction (4 papers, 2021 to 2025). Gross necrosis of the myocardium, as a result of interruption of the blood supply to the area, as in coronary thrombosis. "YY1 plays an important role in early heart development and a protective role in cardiac remodeling after myocardial infarction." (PMID 38364861, 2024). "AntimiR199a therapy up-regulates Sirt1 and inactivates the co-activator P300 protein, thus leading to Yy1 inhibition which decreases both expression and release of circulating sST2 by cardiomyocytes after myocardial infarction." (PMID 33594087, 2021). "YY1 ameliorates cardiac injury and remodeling after myocardial infarction." (PMID 39850120, 2025).
non-Hodgkin lymphoma (4 papers, 2018 to 2022). Distinct from Hodgkin lymphoma both morphologically and biologically, non-Hodgkin lymphoma (NHL) is characterized by the absence of Reed-Sternberg cells, can occur at any age, and usually presents as a localized or generalized lymphadenopathy associated with fever and weight loss. "Therefore, as a whole, the results described the participation of miR-7 with KLF4 and YY1 in the context of non-Hodgkin’s lymphoma, which was consistent with what was reported in other types of cancer." (PMID 36012357, 2022). "We have recently reported that YY1 and KLF4 play a role in non-Hodgkin lymphoma (NHL) and that the expression of KLF4 is regulated by YY1." (PMID 33194748, 2020).
prostate tumor (4 papers, 2009 to 2024). "MiR-186 reduces YY1 expression in lung and prostate tumor cells by binding to sequences at the 3′ UTR region of YY1 mRNA, leading to decreased cell migration and invasion." (PMID 38339244, 2024). "We used Bioinformatic gene RNA array datasets for the expression of YY1 in prostate tumor tissues as compared to normal tissues." (PMID 25053986, 2014). "Meanwhile, previous studies have revealed that miR-186 could downregulate YY1 expression in lung and prostate tumor cells through binding to complementary sequences at 3′ UTR region of YY1 mRNA, leading to decreased cell migration and invasion." (PMID 37444616, 2023).
renal carcinoma (4 papers, 2022 to 2024). A carcinoma arising from the epithelium of the renal parenchyma or the renal pelvis. "We first measured the ratio of renal cancer cells in each phase of the cell cycle, and the results indicated that the loss of both KDM5C and YY1 caused an increased ratio of 769-P tumor cells arrested in the G2/M phase." (PMID 39433896, 2024). "Western blot, quantitative real time PCR (RT‒qPCR), RNA immunoprecipitation PCR (RIP-qPCR), methylated RIP-qPCR (MeRIP-qPCR) and RNA sequencing (RNA-seq) analyses were applied to study the YY1/HDAC2/YTHDC1/ANXA1 axis in renal cancer cells." (PMID 35974388, 2022). "Additionally, it has been documented that PTEN/PI3K/Akt1 signaling regulates YY1 expression, at least in renal cancer cells." (PMID 39063014, 2024). "Next, we examined whether YY1 transcriptionally regulated the expression of YTHDC1 in renal cancer cells." (PMID 35974388, 2022). "We also showed that YY1 inhibition reduced the phosphorylation of ERK in renal cancer cells." (PMID 35974388, 2022). "Interestingly, we found that the HDAC2/YY1 complex suppressed YTHDC1 expression in renal cancer cells." (PMID 35974388, 2022). "To achieve this goal, we first selected human kidney proximal tubular epithelial cell line (HK-2), and several renal cancer cell lines (ACHN, 769-P and RCC4) with different KDM5C and YY1 protein expression levels, as described in our previous studies." (PMID 39433896, 2024). "We also showed that coknockdown of HDAC2 and YY1 did not further increase the expression of YTHDC1 in renal cancer cells." (PMID 35974388, 2022).
renal cell carcinoma (4 papers, 2015 to 2023). "In renal cell cancer, lncRNA LINC02532 upregulated radioresistance via miR-654-5p/YY1 axis." (PMID 35600868, 2022).
sarcoma (4 papers, 2016 to 2025). A usually aggressive malignant neoplasm of the soft tissue or bone. "In sarcoma, the mutation of tubulin gamma complex-associated protein 5 (TUBGCP5) gene reduced the expression of YY1." (PMID 35791393, 2022). "Notably, several SWIFT domain-interacting TFs represented top dependencies in the cancer cell lines in which interactions were identified such as BPTF and TERF2vin ES cells and YY1 and MAX in U2OS sarcoma cells." (PMID 40766474, 2025).
stomach adenocarcinoma (4 papers, 2014 to 2023). "Results showed that levels of YY1 mRNA were significantly increased in numerous stomach adenocarcinoma samples compared with normal tissue samples (left)." (PMID 24970812, 2014). "Furthermore, expressions of YY1 mRNA were higher in stomach adenocarcinoma samples than in their corresponding normal-tissue counterparts from 30 patients with stomach adenocarcinoma (right)." (PMID 24970812, 2014). "Bioinformatics analysis, H. pylori lipopolysaccharide (LPS), YY1 and CREB silencing, Western blot, luciferase assays, and chromatin immunoprecipitation experiments were performed using the stomach gastric adenocarcinoma cell line AGS." (PMID 37762277, 2023). "The function and clinical significance of YY1 in gastric adenocarcinoma (GAC) have not been elucidated." (PMID 24674326, 2014).
asthma (3 papers, 2021 to 2025). "Moreover, rs72891545, the most significant association signal with asthma exacerbations, has also been predicted to involve the modification of several transcription factor binding sites (ELF1, Myc, Sp4, YY1, Zfx)." (PMID 34442380, 2021).
autoimmune disorders (3 papers, 2017 to 2025). "As with many other medical conditions, ‘autoimmune’ disorders seem invariably to be associated with an increase in pro-inflammatory transcription factors, including NF-kB and YY1." (PMID 37174637, 2023). "NF-kB and YY1 are important regulators of both aspects of classical ‘autoimmunity’, namely antibody production by B-cells and autoreactivity in cytolytic T cells, with consequences for the mitochondrial function in both aspects of autoimmunity." (PMID 37174637, 2023). "Future research should aim to elucidate YY1’s mechanistic role in both autoimmunity and organogenesis, which may facilitate the development of targeted therapeutic interventions." (PMID 40655401, 2025).
bone cancer (3 papers, 2014 to 2017). A primary or metastatic malignant neoplasm affecting the bone or articular cartilage. "Depletion or knockdown of YY1 significantly decreases the tumorigenesis and aggressiveness of bone cancer cells." (PMID 28827574, 2017).
chronic kidney disease (3 papers, 2014 to 2023). Impairment of the renal function secondary to chronic kidney damage persisting for three or more months. "Reduced levels in muscle of mice with Chronic kidney diseases (CKD) lead to increased levels of YY1 protein inhibiting the satellite cell differentiation and muscle regeneration." (PMID 25018733, 2014). "Furthermore, YY1 has been reported to convey multiple functions in chronic kidney disease (CKD)." (PMID 37507403, 2023). "Our results proved that RCAN1.4 expression was decreased in vivo and in vitro, in addition to the up-regulation of Yin Yang 1 (YY1), a transcription factor that has been reported to convey multiple functions in chronic kidney disease (CKD)." (PMID 37507403, 2023).
dementia (3 papers, 2020 to 2022). Loss of intellectual abilities interfering with an individual's social and occupational functions. "Are the detrimental effects of YY1 across a host of diverse medical conditions, including cancers, dementia, and type I diabetes, a consequence of melatonergic pathway suppression?" (PMID 36613794, 2022).
endometrioid endometrial adenocarcinoma (3 papers, 2013 to 2021). "miR-193a-5p targets YY1-APC regulatory axis in human endometrioid endometrial adenocarcinoma." (PMID 23387986, 2013).
HCMV infection (3 papers, 2021 to 2025). "Previous studies have demonstrated that YY1 is highly expressed in the latent phase of HCMV infection and acts as a crucial factor for HCMV latency." (PMID 40668819, 2025). "Decondensation of L1 through this mechanism could facilitate the binding of L1 transcriptional activators, such as RUNX3 and YY1, whose expression we previously observed to increase upon HCMV infection, further promoting L1 expression." (PMID 40267069, 2025). "Interestingly, our previous analyses have shown that hsa-miR-29a is decreased during latent HCMV infection of CD34+ cells 1.5-fold, suggesting that latent infection may help maintain levels of YY1, although levels of YY1 were never assessed in that analysis." (PMID 34061599, 2021).
latent infection (3 papers, 2021 to 2026). "During latent infection of undifferentiated cell lines, YY1 can bind to the negative regulatory elements of MIEP and inhibit its activity, and HCMV latency cannot be established in the absence of YY1." (PMID 40668819, 2025). "Interestingly, CMV promoters contain YY1 binding motifs, where YY1 was proposed to act as a repressor to favor latent infection." (PMID 41039989, 2026). "Studies have shown that YY1 can bind to the MIEP and repress its activity, likely by recruitment of histone deacetylases, during latent infection of undifferentiated cell lines." (PMID 34061599, 2021). "Given that removing BMPR2 from iPSCs causes them to respond to levels of TGFbeta that are routinely observed in supernatants of latently infected iPSCs, and that it results in reduced levels of YY1, we next tested whether BMPR2 KO-iPSCs are able to establish and maintain latent infection." (PMID 34061599, 2021).